RNU4-70P (RNA, U4 small nuclear 70, pseudogene)
Gene: Small nuclear RNA gene on chromosome 6 (96,649,453 to 96,649,591, reverse strand). Ensembl gene ENSG00000207309.
Homologues: Orthologues: chimpanzee U4 (98% identical), macaque U4 (95% identical), rabbit U4 (65% identical), guinea pig U4 (52% identical), mouse Gm56237 (49% identical). Paralogues in human: RNU4-12P (86% identical), RNU4-13P (78% identical), RNU4-23P (78% identical), RNU4-67P (78% identical), RNU4-7P (78% identical), RNU4-58P (77% identical), RNU4-45P (76% identical), RNU4-76P (76% identical), RNU4-92P (76% identical), RNU4-68P (76% identical), RNU4-8P (76% identical), RNU4-35P (74% identical), and 81 more.